IL17A (interleukin 17A)
Diseases named in the same sentence as IL17A in open-access papers (continued):
Sharing a sentence is not in itself a finding about the gene and the disease.
infection (continued). "Although the role of IL-17A in Mtb infection is not well studied, it appears to play an important role in the generation of protective immune responses in the lung during early infection." (PMID 28475642, 2017). "Interestingly, the ability of γδ T cells to produce cytokines (IL-17A and IFN-γ) decreased as the infection progressed." (PMID 28507072, 2017). "We did not observe any significant production of IL-17A by stimulated OT-I cells at any time-point during infection." (PMID 29284034, 2017). "Levels of some chemokines and cytokines, such as MIP-2, MCP-1, IL-6, IL-17A, and IFN-γin colons were significantly attenuated in S100A4−/− mice after C. rodentium infection, which suggested reduced inflammation during early infection." (PMID 28935867, 2017). "Multifunctional Th17 cells (IFN-γ+IL-17A+) co-expressing CXCR3/CCR6 are known to upregulate the ligands for CXCR3 (CXCL9/CXCL10/CXCL11) on the lung parenchymal cells, which helps to recruit Th1 cells to the site of infection." (PMID 28985739, 2017). "Furthermore, IL-17A is an inducer of antimicrobial peptides including the β-defensins and lipocalin 2 (LCN2) that prevent infection at mucosal surfaces." (PMID 29048384, 2017). "In addition to IL-17A, γδT cells have emerged as the source of other proinflammatory cytokines, such as interferon (IFN)-γ, in multiple models of infection." (PMID 28912779, 2017). "This indicates the recruitment of γδT cells from the spleen to the lung after infection (IL-17A+Vγ1+γδT subset flow chart and histogram not shown)." (PMID 28912779, 2017). "Not only the percentage of IL-17A+ in CD19+ B cells, but also of its subgroups, including CD1dhighIL-17A+, CD1dlowIL-17A+, CD5+IL-17A+, CD5−IL-17A+, CD1dhighCD5+IL-17A+, CD1dhighCD5−IL-17A+, CD1dlowCD5+IL-17A+, and CD1dlowCD5−IL-17A+, were elevated post-infection." (PMID 28732522, 2017). "An absence of IL-17A or the IL-1 receptor was associated with reduced neutrophil recruitment to the site of infection; and clearance of GAS was significantly attenuated in IL-17A−/− mice and Rag1−/− mice (that lack mature lymphocytes) but not in mice deficient for the IL-1 receptor." (PMID 27241677, 2016). "Although Th17-derived IL-17A is known to recruit neutrophils and enhance inflammation in extracellular infections, a direct intracellular protective effect has not been previously reported." (PMID 27695083, 2016). "Following infection of these cells, we treated them with IFN-γ or IL-17A for 48 hours." (PMID 27695083, 2016). "In summary, we showed that one dose of 4C-Staph/T7-alum vaccine elicits a fast and efficacious protection against S. aureus systemic as well as peripheral infection through the induction of vaccine-specific functional antibodies, CD4+ effector T cells, and IL-17A." (PMID 26812180, 2016). "Overall, this suggests that studies utilizing mice strains lacking expression of IL-17A or the IL-1R can adequately serve as model systems to address the role of these important cytokines in coordinating host responses to infection." (PMID 27241677, 2016). "To clarify the role of Dectin-2 in the host response to S. pneumoniae infection, we compared the production of proinflammatory cytokines and chemokines, such as IL-1β, TNF-α, IL-6, IFN-γ, IL-17A, and MIP-2, in BALF between WT and Dectin-2KO mice 12 h after infection." (PMID 26727976, 2016). "This may impact the course of infection, as IFN-γ can activate bovine phagocytes, and IL-17A has been shown to augment the response of mammary epithelial cells to stimuli of bacterial origin." (PMID 26375594, 2015). "The percentage of IFN-γ+CD3+ T cells and IL-17+CD4+ T cells in spleen, as well as the levels of IFN-γ, IL-17A/F and CCL3 in spleen and lung, significantly increased in the MAP27-immunized mice after infection." (PMID 26317210, 2015).
infection (continued). "Taken together, these data demonstrate that infections and inflammatory conditions can induce IL-17A production in a fraction of Foxp3+Tregsin vivo, but do not affect their immunomodulatory functions." (PMID 25790134, 2015). "Although infiltrating neutrophils were recruited to the tongue following infection, they did not express the IL-17A reporter." (PMID 26213975, 2015). "Of note, secreted Th1 and Th17 cytokines, interferon-γ and IL-17A, did not concomitantly increase in response to gpr4Δgpr5Δ infection." (PMID 25764512, 2015). "Taken together, these results indicate that Th1 cells are sufficient to protect against the infection of H. pylori in the absence of IL-17A." (PMID 26434384, 2015). "The contribution of the surrounding liver tissue, however, was quite significant for other ones, e.g. IL-12, IFN-γ, IL-4 and IL-17A, at the early stage of infection; CXCL9, IL-4, IL-5, CCL17, at the middle stage; and IL-10 and TGF-β at the late stage of infection." (PMID 24637903, 2014). "Results suggest that heat-killed C. neoformans increased the expression levels of IFN-I, IL-1β and IL-6 in the acute phase of infection and enhanced IL-17A production after 2 h (data not shown)." (PMID 24660033, 2014). "Our data showed that IL-1β driven neutrophil recruitment during the first 24 h of infection was mediated by lL-17A, while it became independent of IL-17A at later time points during the exacerbation." (PMID 24918427, 2014). "Of note, although the scope of the study was not to evaluate all sources of IL-17A during infection of vaccinated mice, anti-IL-17A administration would have neutralized IL-17A secreted by all cell types, not just vaccine-primed Th17 cells." (PMID 24465206, 2014). "Here we demonstrated that high IL-17A production in the chronic phase of infection is not essential to anti-T." (PMID 25140115, 2014). "As seen in the experiments with T cells from healthy control individuals, memory CD4+ T cells from patients with CF produce significant amounts of IL-17A, IL-22 and IFN-γ in response to DC infection with either laboratory or clinical PA strains compared with uninfected DCs." (PMID 24587305, 2014). "We found elevated levels of IL-22 through the infection in IDO1-deficient mice in which high levels of IL-17F, but not IL-17A, were also higher as compared to wild-type mice." (PMID 23853597, 2013). "In contrast, the ω-3 PUFA supplemented group was unable to induce such responses during infection evident by the lack of induction of IFN-γ, TNF-α, IL-17A, IL-22 and IL-23, as well as the chemokine Relm-β compared to pre-infection expression." (PMID 23405155, 2013). "Several cytokines, such as the granulocyte macrophage colony-stimulating factor (GM-CSF), IL-1α, TNF-α, IL-10, IL-17A, IL-2, IL-4 and IL-5, showed a slight but non-significant increase in their serum concentrations upon infection (data not shown)." (PMID 23776551, 2013). "Nonetheless, IL-17A has a much greater synergistic effect in combination with live RSV, which suggests that RSV replication is highly relevant for potent induction of local IL-8 expression during infection." (PMID 24194936, 2013). "The peak IL-6 level was most prominent in patients with SAI, while that of IL-17A was most apparent in PI patients without infection." (PMID 23936327, 2013). "In addition, IL-17A has been reported to be required for the development of cytotoxic and humoral responses, therefore parasite-specific adaptive immune responses may be undermined in T. cruzi infected mice lacking IL-17RA signaling contributing to reduced resistance to infection." (PMID 22577359, 2012). "The serum levels of IFN-γ and IL-17A were low and were not affected by the infection or by the estradiol treatment." (PMID 22507741, 2012). "We failed to observe production of IL-17A in lung or spleen homogenates that was significantly different from uninfected controls at any time point after infection (data not shown)." (PMID 22428026, 2012).
infection (continued). "IL-17A transcript levels were significantly increased in the lungs of TLR2−/− mice, in response to enhanced infection and inflammation and may contribute to increased and persistent neutrophilic inflammation in these mice." (PMID 22724018, 2012). "However, the combination of IFN-γ and IL-17A induced significantly higher levels of iNOS activity and NO production than IFN-γ alone in Cm-infected TC-1 cells at each time point after infection." (PMID 22745717, 2012). "The levels of myeloperoxidase (as neutrophil marker), TNFα, INFγ, GM-CSF, IL-1β and IL-6 transiently increased in lungs after infection, while levels of IL-10, IL-17A and IL-22 were indistinguishable from PBS controls." (PMID 22319619, 2012). "The 2W:I-Ab+ cells from IL-6-/- mice had proliferated in response to infection with GAS-2W streptococci but failed to produce IL-17A." (PMID 21966268, 2011). "Previous studies in our laboratory have shown that infection with an IFN-γ-producing C. neoformans strain, H99γ, results in a significant increase in pulmonary IL-17A cytokine production on day 7 post-inoculation compared to mice infected with the parental C. neoformans strain H99." (PMID 21359196, 2011). "On the contrary, IL-17A neutralization during the infection did not influence at all the subsistence and growth of this bacterium in PBS-immunized mice." (PMID 21264260, 2011). "Accordingly, the anti IL-17A shortened the time to death in a lethal infection setup of 5×LD50 (data not shown)." (PMID 20585449, 2010). "Results suggest that CD4+ cells are the major contributors to IL-17A production in infected LVS lungs, yet γδ T cells may have a role in the initial phase of infection." (PMID 20585449, 2010). "Systemic administration of 3 μg of IL-17A (intraperitoneal injection) on the day of infection and on day 3 did not provide any benefit when compared to the control PBS treatment." (PMID 20585449, 2010). "Similar results were obtained when IL-17A was administered one day before the infection (data not shown)." (PMID 20585449, 2010). "As opposed to IL-17A, even a single systemic administration of 3 μg of IL-23 (intraperitoneal injection) on the day of infection provided a moderate, yet statistically significant, benefit when compared to the control PBS treatment." (PMID 20585449, 2010). "Finally, our data demonstrate that the host defends itself against both infections by similar mechanisms, and that adaptive immunity to both organisms required CD4+ T cell production of both IFN-γ and IL-17A." (PMID 20041174, 2009). "However, vaccine-induced protective immunity against both infections required CD4+ T-cell-derived IFN-γ and IL-17A, and functional phagocytic effectors." (PMID 20041174, 2009). "Besides, IL-17A-producing Vγ4 and Vγ6 TCR γδ T cells, which expanded during infection, may have been recruited from other organs." (PMID 40127923, 2025). "However, we did not observe a significant increase in IL-17A producing T cells in murine lungs when we infected with a Beijing strain at 3 weeks post infection." (PMID 40463021, 2025). "Il22−/− mice, with or without FT, displayed induction of IL-17A, IL-17F, and IL-10 upon infection." (PMID 41361166, 2025). "Finally, increases in IL-17A in the lungs following nontypeable Haemophilus influenzae secondary infection promote the establishment of MHV68 latency." (PMID 41335125, 2025). "The increased frequency of IL-17A-producing T cells in the lungs of BCG and ARM groups highlights their potential to strengthen mucosal immunity, as IL-17A plays a crucial role in recruiting Th1 cells for infection control and promoting bacterial killing by neutrophils and macrophages." (PMID 40895571, 2025). "Furthermore, we demonstrated that the host failed to induce sufficient Th17 cells/IL-17A during PmA infection, as evidenced by the significant reduction in Pm-induced mortality following exogenous supplementation of Th17 cells/IL-17A." (PMID 41402924, 2025).
infection (continued). "Interestingly, IL-9 and IL-17a were found in higher concentrations following infection with all three viruses, irrespective of the mouse strain." (PMID 39466030, 2024). "This study utilized human cervical tissue explants as an infection model to demonstrate that GC inoculation increases the secretion levels of both the proinflammatory cytokines IL-1β and TNF-α and the antiinflammatory cytokines IL-10 but not TGF-β and IL-17A during the first 24 hours of infection." (PMID 39585777, 2024). "The number and percentages of IFN-γ+ CD4+ T cells, IFN-γ+ γδ+ T cells, and particularly IL-17A+ CD4+ T cells and IL-17A+ γδ+ T cells in lung of EPS301-adjuvanted mice was markedly higher than that in other groups on day 112 post vaccination in response to infection." (PMID 39556597, 2024). "Compared to the non-infection group, we observed elevated levels of the majority of measured cytokines (25/48) in the CSF during Mtb infection, including TNF-α, IFN-γ, IL-1β, IL-2, IL-3, IL-6, IL-8, IL-10, IL-12(p40), IL-17A, IL-18, IP-10, MIG, MCP-3, MIP-1α, and MIP-1β." (PMID 38047697, 2024). "IL-17A, IL-17F, IL-17C, and IL-17E perform a variety of yet not fully known roles mediating inflammation in autoimmune, allergy, and chronic inflammatory disorders in addition to functioning in host defence against infections at epithelial interfaces." (PMID 37373452, 2023). "Along similar lines, we reported the double-edged role of IL-17A; while protective against Streptococcus pneumonia (Spn) colonization in NP, Influenza A Virus (IAV) triggered a robust IL-17A response that converted asymptomatic bacterial colonization into an invasive infection." (PMID 38060620, 2023). "This may be due to the transient nature of IL17A increasing in serum in response to H. bilis infection in this model; IL17A was expressed at 2 weeks post-H. bilis infection, but not at 6.5 weeks post-infection." (PMID 37764666, 2023). "Furthermore, we identified a population of skin IL-17A-producing Vγ6+ cells, located in proximity to adipocytes in the subcutaneous adipose tissue, that display features of TCR engagement and T cell activation upon infection." (PMID 37644007, 2023). "After infection with Citrobacter rodentium (C. rodentium) in mice, a murine model for enteropathogenic Escherichia coli (EPEC)/enterohemorrhagic Escherichia coli (EHEC) intestinal diseases in humans, RELMα exacerbates intestinal inflammation through promoting the IL-23p19/IL-17A immune axis." (PMID 36691020, 2023). "It is not known whether the increase in IL-17A at 4 dpi relates to an increase in T cell infection and modulation of antigen-presenting cell functions, such as macrophages." (PMID 37631976, 2023). "T helper 17 cells (CD4-positive [CD4+] IL-17A+ and CD4+ IL-17F+), IL-17A- and IL-17F-producing CD8+ T cells, IL-17A-producing γδ T cells, and IL-17A-producing innate lymphoid cells (ILCs) were significantly increased in the skin samples 14 days after infection." (PMID 36695588, 2023). "By using a mouse model of excisional cutaneous wounds co-infected or not with S. aureus and P. aeruginosa, we show that the infection specifically increases the expression of IL-17A, IL-17F and IL-22, and that these cytokines are responsible for the delayed wound healing observed in infected wounds." (PMID 36275755, 2022). "Although an increased adaptive CD44hi CD27neg Vγ4 T cell response may contribute to foodborne Lm resistance of C57BL/6 mice aged 19 or more months, neither anti-TCRδ or anti-IL-17A treatment impacted Lm colonization after primary infection." (PMID 35501808, 2022). "Similar to the ELISA results, cytokine array analysis showed that pulmonary infection with P. aeruginosa PAO1 resulted in significantly increased expression of IL-17A in the WT mice (P < 0.05), whereas IL-17A was not detectable in the infected IL-17A−/− mice 24 h after infection (data not shown)." (PMID 36033859, 2022).
infection (continued). "In contrast, IL-17A KO mice pre-injected with recombinant IL-17A could not improve the survival rate of the infection." (PMID 35221923, 2022). "They scavenge apoptotic epithelial cells during involution, but their contribution to the immune defense of the MG against infections was not investigated, although they express anti-inflammatory (IL-10) and Th17-related (IL-23, IL-22 an IL-17A) modulatory pathways during lactation." (PMID 35464360, 2022). "As IL-17A has been shown to play a devastating role in lung infections, we aimed to examine whether AI-2 can increase the levels of IL-17A and proportion of Th17 cells in the lungs after PAO1 infection." (PMID 36033859, 2022). "Regarding the concentration of cytokines in splenocyte culture supernatants, the infection without subsequent stimulation did not result in significant increases in the concentration of cytokines, with exception of IL-17a at day 7 after infection (data not shown)." (PMID 35795182, 2022). "Additionally, while all unvaccinated mice fully succumbed to infection in the absence of IL-17A, vaccinated mice neutralized of IL-17A in either the presence or absence of CD4+ or CD8+ T cells exhibited a ~35% survival rate 60 days post WT challenge." (PMID 36229573, 2022). "Furthermore, the cytokines induced by stimulation of cells extracted from the skin with HK S. aureus, namely IL-17A, IL-22, GM-CSF, IFN-γ, and TNF-β, were induced also by epicutaneous infection of human skin with live S. aureus, strengthening the value of this in vitro model." (PMID 33796109, 2021). "Thus, the H1-DDA/TDB-induced accumulation of activated CD4+ T cells during the early phase of infection with Mtb does not seem to be dependent on the expression of IL-23 and IL-17A." (PMID 34351501, 2021). "Though CB3-infected MDA5+/- mice have similar levels of inflammatory cytokines TNF-α, IFN-γ, IL-6, IL-17a, and IL-10 (data not shown) by day 7 following infection, CB3-infect MDA5+/- mice have greater systemic levels of both IFN-α and IFN-β compared to CB3-infected wt mice." (PMID 34804036, 2021). "We infer that IL-17A/F responses may play a dichotomous role in TB, contributing to protection in early infection, but driving pathology when the infection is not controlled and bacterial replication promotes chronic immune stimulation." (PMID 33952677, 2021). "However, it is also possible that diminished expression of IL-17A is no longer sufficient to influence the parameters of long-term infection." (PMID 33824206, 2021). "Taken together with the data showing significantly higher bacterial load in Il17A−/− mice, this provides evidence that Th17 rather than Th1 cells are the critical T cell subset for protective immunity against a primary infection of the nasal mucosa with B. pertussis." (PMID 33976385, 2021). "Low numbers of IFN-γ-producing TRM cells accumulated in the nasal tissue during primary infection of WT mice with B. pertussis, and although these cells were significantly expanded in Il17A−/− mice, these mice did not clear the infection in the nose for up to 60 days." (PMID 33976385, 2021). "Thus, we proceeded to perform a study in order to assess infection outcomes and related immune responses in the absence of IL-17A." (PMID 34240122, 2021). "Within the lung tissue of Clarithromycin-treated mice, we found diminished frequencies and numbers of CD4+ IL-17A+ T cells when compared with mock treatment, while the frequency and numbers of CD4+ IFN-gamma+ T cells were unimpaired 7 days post-infection (p.i.)." (PMID 33595670, 2021). "In order to consolidate the link between IL-17, produced primarily by B. pertussis-specific CD4 TRM cells in the nasal cavity, and Siglec-F+ neutrophils and bacterial clearance, we depleted neutrophils in Il17A−/− mice during primary infection with B. pertussis." (PMID 33976385, 2021).